KRAS (KRas proto-oncogene, GTPase)
Diseases named in the same sentence as KRAS in open-access papers (continued):
Sharing a sentence is not in itself a finding about the gene and the disease.
colorectal cancer (continued). "Interestingly, these POLE mutations were predominantly associated with KRAS, NRAS, BRAF, and/or PIK3CA mutations, commonly found in colorectal cancers." (PMID 35624529, 2022). "Therapeutic targeting of KRAS-mutant colorectal cancer (CRC) is an unmet need." (PMID 35803966, 2022). "For example, G12C KRAS inhibitors cause clinical benefit in KRAS G12C-driven NSCLC but not colorectal cancer and this is related to feedback loops involving EGFR signaling." (PMID 35368084, 2022). "While this drug’s development, clinical activity, and approval is remarkable, G12C is not a common mutation in pancreatic and colorectal cancers with KRAS mutations and sotorasib does not benefit patients with amplified or overexpressed KRAS." (PMID 35216221, 2022). "KRAS mutations are more common than BRAF mutations and are present in 30–40% of colorectal cancers." (PMID 36079062, 2022). "Therefore, there is an urgent need to develop new treatments targeting Akt to enhance the sensitivity of KRAS-mutant colorectal cancer (CRC) cells to CTX." (PMID 36387129, 2022). "We speculated that B3GNT6 might negatively regulate the occurrence and metastasis of colorectal cancer through the KRAS/ERK signal pathway." (PMID 35387659, 2022). "By studying the transcriptomes of paired colorectal cancer cell lines with different KRAS gene mutation status, we found that glucose transporter-1(GLUT1) is continuously up-regulated in KRAS mutant cells, and mutant cells can survive under low glucose conditions." (PMID 35444235, 2022). "Cetuximab, first described inhibiting EGFR in 1988, was accepted for clinical use in the KRAS wild-type colorectal cancer (CRC) treatment, leading to the first routine genotyping of CRC patients, since somatic mutations of KRAS were found to confer cetuximab resistance." (PMID 35626010, 2022). "It was reported previously that activation of YAP signaling could bypass both β-catenin dependency in colorectal cancer and KRAS dependency in pancreatic cancer." (PMID 35536676, 2022). "The chromosomal instability (CIN) pathway is usually driven by sequence mutation events, the most common being KRAS, which leads to typical aneuploid microsatellite stable (MSS) colorectal cancer, and the sequence mutation event that drives CIN is more likely to be KRAS than BRAF." (PMID 35387659, 2022). "The aberrant activation of KRAS signaling is a common driver of tumor development and progression in different types of cancers, including pancreatic cancer, non-small-cell lung cancer, colorectal cancer and melanoma, and pancreatic cancer." (PMID 36033462, 2022). "Amplification of ERBB2, or the HER2 gene, is seen in up to 5% of KRAS wild type colorectal cancer." (PMID 35565354, 2022). "Currently, the National Comprehensive Cancer Network (NCCN) advises that colorectal cancer patients with any KRAS or NRAS mutation will not benefit from anti-EGFR therapy." (PMID 35045886, 2022). "Moreover, EGFR cross talks with integrin αvβ3 signaling to activate ERK1/2 and PD-L1 expression in mutant KRAS colorectal cancer (CRC)." (PMID 35705962, 2022). "In clinical practice, KRAS status has been used to determine whether colorectal cancer patients should receive chemotherapy, bevacizumab, or cetuximab." (PMID 36172359, 2022). "Previous studies have shown that KRAS codon 13 mutation is an independent factor for metachronous distant metastasis of colorectal cancer, but there is no conclusive evidence for MLM currently, so this study focuses on the effect of RAS genes on MLM." (PMID 35279173, 2022). "Further evaluation of the recommended molecular biomarkers for colorectal cancers, including more number of codon of KRAS, NRAS and BRAF, may also be required." (PMID 36083889, 2022).
colorectal cancer (continued). "Indeed, in combination with rapamycin, PEG-L-ASNase significantly suppressed the growth of KRAS-mutant colorectal cancer." (PMID 35205650, 2022). "KRAS G12C was widely detected across the primary organ (9% for non–small-cell lung cancer, 3.9% for appendiceal cancer, 3.2% for colorectal cancer, 1.6% for tumor of unknown origin, 1.4% for small bowel cancer, and 1.3% for pancreatic cancer)." (PMID 36088851, 2022). "B3GNT6 levels in colorectal cancer patients were associated with CIN and KRAS mutation status." (PMID 35387659, 2022). "Specific shRNA knockout of ACSL4 could inhibit erastin-induced ferroptosis in KRAS mutant DLD-1 cells, indicating that ACSL4 was a key regulatory molecule for bromelain to effectively inhibit KRAS mutant colorectal cancer by stimulating ferroptosis." (PMID 35910359, 2022). "As TRPC1 can potentially regulate MAPK signaling cascades through KRAS in liver and colorectal cancer cells lines, it would be interesting to further investigate the interplay between TRPC1, KRAS, and the metabolic changes implicated in the acidification of the tumor microenvironment of PDAC." (PMID 36230869, 2022). "Efficacy of sotorasib monotherapy in other KRAS G12C-mutant colorectal cancers was less impactful." (PMID 36284306, 2022). "Conversely, when the presence of a variant allele is contraindicative for therapy (e.g., KRAS variant positivity and anti-EGFR treatment in colorectal cancer), variant-enriched expression may negatively impact treatment outcomes." (PMID 36675685, 2022). "As our meta-analysis cohort did not include colorectal cancers, we are unable to discern the role of KRAS mutations in treatment response for these cancers." (PMID 35803911, 2022). "Another study established a IRG signature in KRAS-mutant colorectal cancer based on four IRGs." (PMID 36440228, 2022). "In addition to leukaemia, KRAS has been a major driver of colorectal cancer, lung cancer and other cancers, so next we will establish tissue-specific tumours by using different KRAS mutants." (PMID 34797366, 2022). "Similarly, sotorasib and panitumumab combination in CodeBreaK101 study also showed an ORR of 16.6% and DCR of 83.3% in KRAS G12C-mutant colorectal cancer." (PMID 36284306, 2022). "Hence, aiming at perceiving KRAS-autonomous versus -non autonomous mechanisms, we studied the response of two mutant KRAS colorectal cancer cell lines (HCT116 and LS174T) upon KRAS silencing and treatment with rhTGFβ1-activated fibroblasts secretome." (PMID 35805073, 2022). "Unlike the canonical adenoma-carcinoma sequence, SPs are proven to be early precursors to about 15%–30% colorectal carcinoma (CRC) through serrated pathway, frequently associated with BRAF or KRAS oncogenic mutations, microsatellite instability (MSI), and high CpG island methylator phenotype (CIMP)." (PMID 35402217, 2022). "This suggests that while DHX38/PRP16 growth dependency in colorectal carcinoma cells may rely on KRAS, the link between the two in other cancers, including OCCC, may not be as strong." (PMID 34965029, 2022). "Additionally, KRAS status will shift the metastatic profile of colorectal cancer; KRAS-mutant tumors tend to spread to the lungs, whilst wild-type tumors have a higher propensity of invasion to the liver." (PMID 34301278, 2021). "This combination has also shown success in KRAS mutant colorectal cancer." (PMID 34828525, 2021). "Some clinically relevant genes may encounter pseudogenes, such as KRAS for colorectal cancer and BRCA1 for ovarian cancer and breast cancer." (PMID 33916923, 2021). "One patient had a colorectal cancer harboring both, B2M and KRAS mutations, but did not receive ICB." (PMID 34168989, 2021).
colorectal cancer (continued). "Therefore, there is an ongoing dire need to improve on targeted cancer therapies for the management of KRAS-positive colorectal cancer cases." (PMID 33959410, 2021). "Here, we further investigated whether cetuximab-mediated regulation of p38/Nrf2/HO-1 promotes RSL3-induced ferroptosis and plays a pivotal role in overcoming drug resistance in KRAS mutant colorectal cancer (CRC)." (PMID 34775496, 2021). "The mutation of KRAS is related with the resistance to EGFR-targeted therapeutics, and the loss of the tumor suppressor PTEN implies more aggressive tumorigenesis from these patients with advanced colorectal cancer." (PMID 35003350, 2021). "Evidence coming from other in vitro and in vivo studies demonstrated efficient induction of apoptosis in KRAS or BRAF mutant colorectal cancer cell lines treated with navitoclax in combination with the TORC1/2 inhibitor AZD8055 but not in the wild-type controls." (PMID 33777798, 2021). "As a result, colorectal cancer patients harboring KRAS or NRAS have shorter overall survival (OS)." (PMID 34301278, 2021). "However, the specific molecular mechanisms by which DDX3X promotes metastasis are different in colorectal cancers harbouring wild-type or mutant KRAS." (PMID 33627125, 2021). "Additionally, in colorectal cancer harbouring mutant KRAS, DDX3X stabilizes β-catenin via the CK1ε/Dvl2 axis to promote invasiveness." (PMID 33627125, 2021). "In fact, KRAS is involved in several cancers, notably colorectal cancers." (PMID 34270548, 2021). "Additionally, KRAS and BRAF hot-spot mutations were identified using the DTBP platform, with >71% correlation between tissue and frozen plasma samples of 30 colorectal cancer patients." (PMID 33925308, 2021). "Therefore, β-elemene can be used as a novel pro-mast disease inducer to inhibit the migration of KRAS-mutated CRC cells and enhance the sensitivity of KRAS-mutated colorectal cancer cells by combining with cetuximab to induce ferroptosis and inhibit EMT." (PMID 34641334, 2021). "However, it was also reported that SIRT5-positive colorectal cancer cells with wild-type KRAS were resistant to either chemotherapeutic agents or cetuximab; SIRT5 promoted cisplatin resistance in ovarian cancer." (PMID 33516270, 2021). "Regarding the induction of NET formation, KRAS mutation has been shown to contribute to neutrophil recruitment and NET formation through exosomes in colorectal cancer, which uncovered a novel mechanism of regulation of NET formation in colorectal cancer." (PMID 34476216, 2021). "Similarly, in KRAS mutant colorectal cancer cells, the upregulation of GLUT1 and consequent fluorodeoxyglucose accumulation was observed by PET." (PMID 33925206, 2021). "In 18 patients with KRAS G12C mutant colorectal cancer (CRC), 13 achieved SD27." (PMID 34845311, 2021). "Fc-gamma receptor polymorphisms were associated with efficacy but not with toxicity in wild-type KRAS, cetuximab-treated colorectal cancer patients." (PMID 34285919, 2021). "Furthermore, overexpression of miR-19A inhibits colorectal cancer angiogenesis by suppressing KRAS expression." (PMID 33591950, 2021). "To directly compare the effects of KRAS and BRAF mutations in a genetic background originally dependent on pathway mutation, we engineered KRAS G12C, G12D, G12V and G13D mutations in colorectal cancer RKO cells where the mutant BRAF V600E allele had been removed." (PMID 34233735, 2021).
colorectal cancer (continued). "Consistently, IPA revealed that C10 in both species are enriched for signaling pathways involved in multiple malignancies associated with KRAS mutation, i.e., NSCLC, as well as colorectal cancer, pancreatic ADC, ovarian cancer, acute myeloid leukemia, melanoma, and endometrial cancer." (PMID 33854168, 2021). "Moreover, therapeutic experiences clearly indicated that hEx3, unlike conventional anti-EGFR antibodies, was effective against colorectal cancer (CRC) cells with mutant KRAS, BRAF, or PIK3CA." (PMID 32666260, 2021). "Various CRISPR systems have been used to target KRAS in colorectal cancer (CRC)." (PMID 34781949, 2021). "However, oncogenic KRAS promotes tumor cell immune escape and immune therapy resistance through attracting immune-suppressive cells or suppressing cytotoxic cells in a colorectal cancer mouse model." (PMID 34301278, 2021). "Notably, PIK3CA mutations have been found to have a synergistic effect with mutational inactivation of PTEN in inducing drug resistance or in inducing poor prognosis with EGFR/KRAS comutations in nonsmall cell lung and colorectal cancer." (PMID 33827485, 2021). "On the other hand, it has been shown that inhibition of autophagy sensitizes KRAS-mutant colorectal cancer cells to concurrent use of glycolysis and mevalonate pathway inhibitors, suggesting that multiple metabolisms may be targeted simultaneously." (PMID 34946644, 2021). "We investigated whether rigosertib, a benzyl styryl sulfone RAS signaling disruptor, could selectively kill KRAS-mutant colorectal cancer cells." (PMID 34347396, 2021). "Another PI3K inhibitor, BKM120, was found to impede KRAS mutation-induced colorectal cancer growth both in vitro and in vivo, regardless of PI3K genotype." (PMID 34663410, 2021). "KRAS mutation is a predictive biomarker commonly used in colorectal cancer to identify patients who will not benefit from treatment with drugs against epidermal growth factor receptor (EGFR)." (PMID 32885400, 2021). "Therefore, the present study was aimed at identifying anti-mKRAS antibodies for KRAS colorectal cancer by utilizing phage display libraries to screen for antibodies that selectively target G12V and G13D KRAS-positive colorectal cancer cells." (PMID 33959410, 2021). "At present, the relationship between autophagy and KRAS in colorectal cancer remains obscure." (PMID 33995628, 2021). "We hypothesised that plasticity in signal transduction may be a mechanism of drug resistance and tested this hypothesis in the setting of cetuximab resistance in patients with KRAS/NRAS/BRAFV600 wild-type colorectal cancer (CRC)." (PMID 34462871, 2021). "Mutations in the KRAS genes also cause changes in enzymes involved in pathways of glucose metabolism such as glucose uptake, amino acid metabolism, and pentose phosphate, as well as the mitochondrial pathway of OXPHOS of colorectal cancer." (PMID 34840582, 2021). "A recent study showed that KRAS G12C mutations occur between 3–14% of different cancer types including NSCLC, colorectal cancer, appendiceal, and small bowel cancer, suggesting also that, in NSCLC, female patients harbored significantly more KRAS G12C mutations than male patients." (PMID 34684076, 2021). "Currently, a ctDNA assay for the detection of EGFR mutations in patients with non-small-cell lung cancer (NSCLC) has been approved by the Food and Drug Administration, and ctDNA assays for EGFR in NSCLC and for KRAS in colorectal cancer are available for commercial use in Europe3,4,45." (PMID 33441840, 2021). "Subsequently, genetic analysis revealed that cetuximab effectively treated colorectal cancers in patients without KRAS mutations." (PMID 34359640, 2021).
colorectal cancer (continued). "It is well-known that KRAS mutations in patients with colorectal cancer, are associated with no response to anti-EGFR therapies and with consequent significantly lower OS and disease-free survival, due to higher risk of tumor relapse, especially in the lungs." (PMID 33946899, 2021). "Therefore, this study reports a proof-of concept approach employing a 3rd generation anti-mKRAS scFv immunotoxin potentially capable of target-specific eradication of KRAS-positive colorectal cancer cells." (PMID 33959410, 2021). "Despite the frequent detection of KRAS driver mutations in patients with colorectal cancer (CRC), no effective treatments that target mutant KRAS proteins have been introduced into clinical practice." (PMID 33982211, 2021). "In addition, the SEER program lacks several important biomarker expression states, such as MSI, NRAS, KRAS, and BRAF, which were closely associated with metastases in colorectal cancer." (PMID 34055605, 2021). "Importantly, KRAS drives 32% of lung cancers, 40% of colorectal cancers, and 85% to 90% of pancreatic cancer." (PMID 34206370, 2021). "From the comparison, KRAS (CA19-9 ≥ 25 and CEA ≥ 5: 77.3%, the others: 40%; p = 0.001) and PTEN (CA19-9 ≥ 25 and CEA ≥ 5: 13.7%, the others: 0.7%; p = 0.007) showed significantly higher mutation frequencies from the 22 patients with advanced colorectal cancer." (PMID 35003350, 2021). "Indeed, the system xCT is overexpressed in several cancer types including colorectal tumours with mutant KRAS and has been found to be strongly correlated with recurrence in colorectal cancer patients." (PMID 33498690, 2021). "KRAS, NRAS, and BRAF mutations are commonly present in colorectal cancer (CRC)." (PMID 33979337, 2021). "The results based on the autophagy-related lncRNAs showed that the KRAS signaling pathway might play an important role in autophagy in colorectal cancer." (PMID 33149738, 2020). "While KRAS G12C is not a common mutation in colorectal cancer, this study is significant in demonstrating treatment efficacy for KRAS inhibitors." (PMID 33238500, 2020). "This strategy may also find application in other EGFR-positive tumours in which CTX has been ineffective, such as in KRAS mutant colorectal cancers." (PMID 32913288, 2020). "Furthermore, KRAS was shown to upregulate the enzyme asparagine synthetase in colorectal cancer via the PI3K-AKT-mTOR pathway, which allows cells to survive and proliferate upon glutamine depletion." (PMID 32932943, 2020). "In addition, KRAS-mediated KAP1/TRIM28 sumoylation is also involved in the KRAS-driven transformation in colorectal cancer." (PMID 32210733, 2020). "In addition, these data lacked the description of the distant metastasis site and the detection of key molecules of colorectal cancer, like KRAS and BRAF." (PMID 32469151, 2020). "Phase three clinical trial evidence suggests that colorectal cancers with the KRAS G13D mutation may benefit from EGFR inhibitors, like cetuximab, in contrast to the other most common KRAS mutations." (PMID 33153459, 2020). "There is evidence of an association between KRAS mutations and response to conventional chemotherapy in colorectal cancer, although other studies have not reached significance, probably due to heterogeneity in stage selection and treatment." (PMID 32784964, 2020). "This suggests that KRAS mutations alone are not sufficient for changes in the epithelial morphology of colorectal cancer cells regarded as necessary for metastasis evolvement." (PMID 33002027, 2020). "Colorectal cancer (CRC) patients with Kristen rat sarcoma viral gene (KRAS) mutant tumors are associated with lack of response to anti-epidermal growth factor receptor (anti-EGFR) antibody therapy." (PMID 33226505, 2020). "Another oncosuppressor which is frequently mutated in colorectal cancer is PTEN, which also could be co-mutated with KRAS (~25%)." (PMID 32725342, 2020).